ZFAND6 (zinc finger AN1-type containing 6)
Description:
Involved in regulation of TNF induced NF-kappa-B activation and apoptosis. Involved in modulation of 'Lys-48'-linked polyubiquitination status of TRAF2 and decreases association of TRAF2 with RIPK1. Required for PTS1 target sequence-dependent protein import into peroxisomes and PEX5 stability; may cooperate with PEX6. In vitro involved in PEX5 export from the cytosol to peroxisomes (By similarity).
Synonyms: AWP1; ZA20D3; ZFAND5B
Tractability: PROTAC: ubiquitination databases record sites on it; its protein half-life has been measured.
Gene: Protein-coding gene on chromosome 15 (80,058,894 to 80,140,292, forward strand). Ensembl gene ENSG00000086666.
Subcellular location: Cytoplasm
Subcellular location (Human Protein Atlas): Nucleoplasm
Pathways (Reactome):
Protein localization: Peroxisomal protein import
Gene Ontology:
Molecular function: protein binding; polyubiquitin modification-dependent protein binding; DNA binding; zinc ion binding
Biological process: cellular response to tumor necrosis factor; negative regulation of apoptotic process; regulation of canonical NF-kappaB signal transduction; protein targeting to peroxisome
Cellular component: cytosol; cytoplasm
Genetic constraint (gnomAD): Loss-of-function variants: 10 observed, 16.94 expected, observed/expected ratio (o/e) 0.59, 90% interval 0.36 to 1. The upper end of that interval is the gene's LOEUF score, 1, which puts it in group 4 of 6, group 1 being the genes least tolerant of losing a copy. Missense variants: 192 observed, 231.63 expected, observed/expected ratio (o/e) 0.83, 90% interval 0.74 to 0.93. Synonymous variants: 90 observed, 78.47 expected, observed/expected ratio (o/e) 1.15, 90% interval 0.97 to 1.37.
Homologues: Orthologues: macaque ZFAND6 (99% identical), pig ZFAND6 (96% identical), dog ZFAND6 (95% identical), mouse Zfand6 (95% identical), rat Zfand6 (94% identical), rabbit ZFAND6 (92% identical), guinea pig ZFAND6 (88% identical), tropical clawed frog zfand6 (63% identical). Paralogues in human: ZFAND5 (58% identical), ZFAND3 (25% identical).
Diseases named in the same sentence as ZFAND6 in open-access papers:
ZFAND6 is named in the same sentence as 7 diseases in open-access papers, as found by Europe PMC text mining. Sharing a sentence is not in itself a finding about the gene and the disease. The quoted sentences say what the papers report.
diabetes (2 papers, 2022 to 2023). "For example, ZFAND6, a zinc finger protein implicated in the pathophysiology of diabetes but not studied in spermatogenesis, shows high conservation across vertebrates in the 3′ UTR." (PMID 36284317, 2022). "Although ZFAND6 and PRC1 were identified as diabetes related loci in western populations, only recently the role of ZFAND6 and PRC1 loci have been described in insulin secretion and beta cell function through animal models." (PMID 37738238, 2023).
type 2 diabetes (2 papers, 2011 to 2023). "We confirm the role of ZFAND6, PRC1 and TMEM154 in the pathophysiology of type 2 diabetes among Indians." (PMID 37738238, 2023).
Obesity (1 paper, 2023). Accumulation of substantial excess body fat. "In conclusion, only five of the 37 genetic variants previously linked to T2DM and obesity in the Saudi Arabian population [HNF4A-rs4812829, WFS1-rs1801214, DUSP9-rs5945326, ZFAND6-rs11634397, FTO-rs11642841] were associated with prediabetes susceptibility." (PMID 36980809, 2023).
prediabetes (1 paper, 2023). "The current study revealed that their variants, including the GA heterozygous of DUSP9 (rs5945326) and GG heterozygous of ZFAND6 (rs11634397) genotypes, contributed to decreased risk of developing prediabetes." (PMID 36980809, 2023). "In summary, we found significant associations between prediabetes risk and five variants closely related to the FTO, HNF4A, WFS1, DUSP9, and ZFAND6 genes (rs4812829, rs1801214, rs5945326, rs11642841, and rs11634397) among Saudi Arabian adults." (PMID 36980809, 2023). "Furthermore, heterozygous GA of rs4812829 (HNF4A), rs5945326 (DUSP9), and rs11634397 (ZFAND6), along with heterozygous TC of rs1801214 (WFS1), were associated with a decreased risk for prediabetes." (PMID 36980809, 2023).
cancer (1 paper, 2021). A tumor composed of atypical neoplastic, often pleomorphic cells that invade other tissues. "Even though the known functional role of AWP1 (zinc finger AN1 type-6, ZFAND6) is as a key mediator of TNF-α signaling, its potential role in the TNF-α-dependent responses of cancer cells remains unclear." (PMID 33816268, 2021).
ZFAND6 also shares sentences with these, for which no sentence is quoted: breast carcinoma (2 papers); tumor (2).